RAB18 (RAB18, member RAS oncogene family)
Description:
The small GTPases Rab are key regulators of intracellular membrane trafficking, from the formation of transport vesicles to their fusion with membranes. Rabs cycle between an inactive GDP-bound form and an active GTP-bound form that is able to recruit to membranes different sets of downstream effectors directly responsible for vesicle formation, movement, tethering and fusion. RAB18 is required for the localization of ZFYVE1 to lipid droplets and for its function in mediating the formation of endoplasmic reticulum-lipid droplets (ER-LD) contacts. Also required for maintaining endoplasmic reticulum structure. Plays a role in apical endocytosis/recycling (By similarity). Plays a key role in eye and brain development and neurodegeneration.
Synonyms: RAB18LI1; WARBM3
Tractability: Small molecule: a structure with a bound ligand is known. Antibody: its Gene Ontology location is reachable by antibodies, with high confidence; UniProt places it where antibodies can reach, with medium confidence. PROTAC: ubiquitination databases record sites on it; its protein half-life has been measured.
Gene: Protein-coding gene on chromosome 10 (27,504,174 to 27,545,117, forward strand). Ensembl gene ENSG00000099246.
Subcellular location: Endoplasmic reticulum membrane; Golgi apparatus, cis-Golgi network membrane; Lipid droplet; Apical cell membrane
Pathways (Reactome):
Vesicle-mediated transport: COPI-independent Golgi-to-ER retrograde traffic; RAB GEFs exchange GTP for GDP on RABs
Immune System: Neutrophil degranulation
Metabolism of proteins: RAB geranylgeranylation
Gene Ontology:
Molecular function: G protein activity; GDP binding; GTPase activity; protein binding; GTP binding
Biological process: endoplasmic reticulum tubular network organization; lipid droplet organization; sterol homeostasis; brain development; eye development; small GTPase-mediated signal transduction
Cellular component: cis-Golgi network membrane; endoplasmic reticulum membrane; endoplasmic reticulum tubular network; lipid droplet; apical plasma membrane; cytosol; Golgi apparatus; plasma membrane; secretory granule membrane
Genetic constraint (gnomAD): Loss-of-function variants: 6 observed, 22.06 expected, observed/expected ratio (o/e) 0.27, 90% interval 0.15 to 0.54. The upper end of that interval is the gene's LOEUF score, 0.54, which puts it in group 2 of 6, group 1 being the genes least tolerant of losing a copy. Missense variants: 163 observed, 206.07 expected, observed/expected ratio (o/e) 0.79, 90% interval 0.69 to 0.9. Synonymous variants: 86 observed, 76.6 expected, observed/expected ratio (o/e) 1.12, 90% interval 0.94 to 1.34.
Gene-disease validity (ClinGen):
ClinGen rates the evidence that RAB18 causes each of these diseases.
Warburg micro syndrome (autosomal recessive): Moderate. Micro syndrome is an autosomal recessive disorder caracterised by ocular and neurodevelopmental defects and by microgenitalia.
Homologues: Orthologues: chimpanzee RAB18 (100% identical), pig RAB18 (99% identical), mouse Rab18 (99% identical), dog RAB18 (99% identical), guinea pig RAB18 (99% identical), macaque RAB18 (98% identical), rat AABR07068154.1 (93% identical), zebrafish rab18b (88% identical). Paralogues in human: RAB1A (46% identical), RAB1B (45% identical), RAB2B (44% identical), RAB2A (44% identical), RAB35 (44% identical), RAB11B (42% identical), RAB4A (42% identical), RAB11A (41% identical), RAB3B (41% identical), RAB8A (41% identical), RAB12 (41% identical), RAB3A (41% identical), and 56 more.
Diseases named in the same sentence as RAB18 in open-access papers:
RAB18 is named in the same sentence as 44 diseases in open-access papers, as found by Europe PMC text mining. Sharing a sentence is not in itself a finding about the gene and the disease. The quoted sentences say what the papers report.
Warburg micro syndrome (20 papers, 2014 to 2025). "For example, Rab18 deficiency detected in both types of challenged RGCs is the molecular deficit underlying Warburg micro syndrome, characterized by eye, nervous system, and endocrine abnormalities." (PMID 37873477, 2024). "In line with this, larger LDs accumulate in fibroblasts taken from patients suffering from mutation in Rab18 called Warburg Micro syndrome further suggests evidence for a role of Rab18 in LD homeostasis." (PMID 39421023, 2024). "Nevertheless, the finding that levels of the same specific sterol are elevated in a second cell type, deficient in a second Micro syndrome gene, provide good evidence that the RAB18–EBP interaction identified in our screening is meaningful." (PMID 37774976, 2023). "RAB18 has been proven to have a role in regulating neuronal migration, and the mutations of RAB18 led to Warburg-Micro syndrome, whose classic phenotype is abnormalities of the brain and eye." (PMID 35456484, 2022). "Martsolf syndrome is the milder form of RAB18 deficiency, while Warburg micro syndrome is the more severe form." (PMID 34702808, 2021). "RAB18 deficiency was assumed to be the underlying mechanism of Martsolf and Warburg micro syndromes." (PMID 34702808, 2021). "Warburg Micro syndrome is a disease characterized by direct loss of RAB18 function or loss of RAB18 activation showing an important role of RAB18 in neuronal development." (PMID 26879639, 2016). "Loss of function mutations in RAB18, has been identified in patients with the human neurological and developmental disorder Warburg Micro syndrome." (PMID 26879639, 2016). "Together with previous reports, this indicates that Warburg Micro syndrome can be caused directly by loss of RAB18, or indirectly through loss of RAB18 regulators RAB3GAP or TBC1D20." (PMID 26063829, 2015). "Loss-of-function mutations in RAB18, which encodes a ubiquitously expressed Rab-associated protein, cause the autosomal recessive disorder Warburg Micro syndrome." (PMID 24764192, 2014). "Mutation of the single Rab18 gene in humans causes the recessive developmental disorder Warburg Micro syndrome." (PMID 25453831, 2014). "Furthermore, gene-disease associations showed substantial overlap with RAB18 deficiency/Warburg Micro syndrome." (PMID 37774976, 2023). "Loss of functional RAB18 causes the autosomal recessive condition Warburg Micro syndrome." (PMID 37774976, 2023). "A number of subsequent studies then further implicated Rab18 in macroautophagy and provided evidence that part of the phenotype of Warburg micro syndrome in which Rab18 or its exchange factor RAB3GAP1/RAB3GAP2 is mutated may be due to impaired macroautophagy." (PMID 33803444, 2021). "RAB18 is a protein with emerging roles in ER to Golgi retrograde trafficking and other cellular trafficking, and LOF mutations in RAB18 are associated with Warburg micro syndrome, establishing a critical role of RAB18 in eye and brain development and neurodegeneration." (PMID 30044992, 2018). "RAB18 mutations have been indentified in patients with Warburg Micro syndrome." (PMID 26879639, 2016). "Warburg micro syndrome (WARBM) and Martsolf syndrome are rare genetic disorders caused by a deficiency in RAB18 protein (OMIM: #212720; #600118)." (PMID 34702808, 2021). "Mutations in RAB18 have been shown to cause the heterogeneous autosomal recessive disorder Warburg Micro syndrome (WARBM)." (PMID 24764192, 2014). "Rab GTPases are also implicated in various disorders including RAB7‐related neuropathy, RAB27A‐related Griscelli syndrome, and RAB18‐Warburg micro syndrome." (PMID 39420677, 2025). "Biallelic loss-of-function variants in RAB18, RAB3GAP1, RAB3GAP2, or TBC1D20 cause the autosomal recessive condition Warburg Micro syndrome (Mendelian Inheritance in Man IDs: 600118, 614222, 614225, 615663, and 212720)." (PMID 37774976, 2023). "Rab18 -/- mice developed as a model of Warburg micro syndrome showed macroautophagy defects in this study." (PMID 33803444, 2021).
Warburg micro syndrome (continued). "Taken together, these studies strongly implicate Rab18 as a regulator of macroautophagy and suggest that the phenotype of Warburg micro syndrome is related in part to dysfunctional macroautophagy due to impaired Rab18 function." (PMID 33803444, 2021). "RAB18, RAB3GAP1, RAB3GAP2 and TBC1D20 are each mutated in Warburg Micro syndrome, a rare autosomal recessive multisystem disorder." (PMID 26063829, 2015). "RAB3GAP1 and RAB3GAP2 were characterized as forming a complex with GAP activity towards Rab3 isoforms before their involvement in Micro syndrome, or that of RAB18, was known." (PMID 26063829, 2015). "The data suggest that the Rab18-knockout mouse represents a robust model for Warburg Micro syndrome, offering a new experimental platform for investigating disease pathogenesis and testing potential therapies." (PMID 24764192, 2014). "Mutations in RAB18, RAB3GAP1, RAB3GAP2, and TBC1D20 have caused Warburg micro syndrome, a rare autosomal recessive multisystem disorder, suggesting that RAB3GAP1, RAB3GAP2, and TBC1D20 might play roles in PRRSV-2 replication." (PMID 38607975, 2024). "It has been demonstrated that mutations in RAB3GAP1 (RAB3 GTPase activating protein catalytic subunit 1), RAB3GAP2 (RAB3 GTPase activating non-catalytic protein subunit 2), and RAB18 (Ras-related protein Rab-18) cause Warburg micro syndrome 1–3 (WARBM1-3)." (PMID 33562517, 2021). "Primarily, our results show that RAB18 is a key regulator during the development of brain in mouse, and may demonstrate an essential role of this gene in pathophysiology of Warburg Micro syndrome in humans." (PMID 26879639, 2016). "The expression pattern of RAB18 in mouse brain together with the observed disease phenotype of Warburg Micro syndrome patients led us to hypothesize that RAB18 is important for the cortical development." (PMID 26879639, 2016). "Rab18 mutant mice are viable and fertile; however, the mutants display phenotypic defects reminiscent of the clinical phenotypes observed in Warburg micro syndrome (WARBM) patients." (PMID 32033485, 2020). "Other disorders implicate defective interaction with Rabs, for example, through Rab5 in ALS2‐related amyotrophic lateral sclerosis, through Rab11 in UNC45A‐ and UNC45B‐related disorders, or through Rab18 in RAB3GAP1‐ and RAB3GAP2‐related Warburg micro syndrome." (PMID 39420677, 2025).
Obesity (7 papers, 2011 to 2025). Accumulation of substantial excess body fat. "Taken together, our results suggest that obesity-related pathogenic processes alter the maintenance of ER–LD interactions and interfere with Rab18 trafficking through these contact sites." (PMID 38139006, 2023). "Rab18 also plays a crucial role in the dynamics of lipid droplets, whose accumulation is a hallmark of obesity." (PMID 35563289, 2022). "Based on our findings on Rab18 in 3T3-L1 cells and given the relationship between human obesity and obesity-associated T2D and altered adipocyte lipid metabolism, we examined Rab18 in human adipose tissue in subjects with different metabolic conditions." (PMID 21829560, 2011). "Indeed, except for the subcutaneous depot in women, obesity was associated with an increase in Rab18 expression, which suggests that upregulation of this GTPase may be an appropriate response to managing energy excess." (PMID 21829560, 2011). "Consistent results were observed in three different murine models of obesity (diet-induced, ob/ob, and New Zealand obese mice), where the expression levels of Rab18 increased in both visceral and subcutaneous adipose tissues." (PMID 38139006, 2023). "Moreover, obesity is associated with an increase in Rab18 expression, which suggests that upregulation of this GTPase may be an appropriate response to managing energy excess, an adaptive response to overcome the alterations in lipid metabolism occurring in obesity." (PMID 25922847, 2015). "Herein, the ER–LD connection and Rab18 distribution at ER–LD contact sites are examined in adipocytes challenged with fibrosis and inflammatory conditions, which represent known hallmarks of the adipose tissue in obesity." (PMID 38139006, 2023). "Another example of up-regulated molecules in obesity is Rab18, which is a GTPase that has been found to regulate intracellular membrane bidirectional trafficking of lipids in lipid droplets; it is involved in the mechanism to release lipids from lipid droplets in adipocytes." (PMID 25922847, 2015). "Finally, we explore the regulation of Rab18 expression in human adipose tissue as a function of sex, adipose tissue localization and obesity." (PMID 21829560, 2011). "Finally, we have demonstrated, for the first time, the presence of Rab18 in human adipose tissue and showed that the expression of this GTPase is correlated to obesity." (PMID 21829560, 2011). "In this scenario, it is tempting to speculate that the enhanced expression of Rab18 in obese individuals is an adaptive response to overcome the alterations in lipid metabolism occurring in obesity." (PMID 21829560, 2011). "Finally, we describe, for the first time, the presence of Rab18 in human adipose tissue, wherein the expression of this GTPase exhibits sex- and depot-specific differences and is correlated to obesity." (PMID 21829560, 2011). "However, it is still unknown as to whether the binding of Rab18 to LDs is disturbed in adipocytes under obesity conditions." (PMID 38139006, 2023). "In addition, our results provide further support for the role of ER–LD bridges as a possible access route for Rab18 to the LD surface in adipocytes, which may be altered in obesity conditions, as occurs upon fibrosis-induced ER fragmentation." (PMID 38139006, 2023). "In addition, included is RAB18 (Ras-related protein Rab-18), acting as a molecular switch between lipogenesis and lipolysis, and having a central role in controlling storage and release of fat and thereby in the development of obesity." (PMID 34585119, 2021). "However, no studies so far have dissected the impact of these obesity insults on Rab18’s interaction with adipocyte LDs." (PMID 38139006, 2023).
gastric cancer (6 papers, 2018 to 2021). A primary or metastatic malignant neoplasm involving the stomach. "Rab18 has been reported to regulate cell proliferation and apoptosis in some cancers, such as hepatocellular carcinoma, gastric cancer, and head and neck squamous cell carcinoma." (PMID 33904378, 2021). "For example, as a tumor suppressor gene, miR-455-5p inhibited the proliferation and metastasis of gastric cancer cells by down-regulating the expression of Rab18." (PMID 34288799, 2021). "RAB18 promoted cell viability, invasion, and migration and impaired cell apoptosis in gastric cancer." (PMID 34135963, 2021). "In this study, the expression of RAB18 was significantly mediated by miR-455, which was consistent with the findings in gastric cancer where miR-455 targeted RAB18 through directly binding to the 3′-UTR of RAB18 mRNA." (PMID 34135963, 2021). "However, miR‐455‐5p expression in gastric cancer was lower, and thus, in cancer miR‐455‐5p functions as a tumor suppressor through regulation of RAB18." (PMID 30444038, 2019). "In humans, this miRNA homologue down regulated RAB18 gene in gastric cancer." (PMID 30208606, 2018). "Moreover, miR-455-5p was reduced significantly in gastric cancer cells and could inhibit human gastric cancer-cell proliferation and invasion, as well as promote cell apoptosis, by targeting a member of the RAS oncogene family (RAB18)." (PMID 31111062, 2019).
microcephaly (6 papers, 2014 to 2024). A congenital or acquired developmental disorder in which the circumference of the head is smaller than normal for the person's age and sex. "For instance, microcephaly has been associated with mutations in RAB3GAP/RAB18, ARFGEF2, ARF1, kinesin KIF2A, or dynein heavy chain, all affecting both membrane trafficking and neuronal morphogenesis." (PMID 39115595, 2024). "No mammalian models for Rab18 deficiency have been reported, although morpholino knockdown of the two RAB18 orthologues in zebrafish results in animals with reduced body size, microphthalmia and microcephaly, reminiscent of the WARBM phenotype." (PMID 24764192, 2014). "Variants in multiple genes regulating endosomal trafficking and/or fusion of secretory vesicles [such as SMPD4, WDFY3, TRAPPC4, RAB18, VPS13B, EXOC7, EXOC8, VPS11], have been associated with the occurrence of microcephaly, cerebral atrophy, and neurodevelopmental delay." (PMID 36538041, 2023).
breast carcinoma (4 papers, 2014 to 2024). "Current studies reported that knockdown of Rab18 inhibited the proliferation of breast cancer cells while its upregulation promoted the proliferation of hepatoma cells." (PMID 33904378, 2021). "The regulations of RAB21, RAB23, RAB18 and RAB3B by miR-200b were further confirmed in breast cancer cell lines." (PMID 24447584, 2014). "The expressions of RAB21, RAB23, RAB18 and RAB3B were suppressed by transfection of miR-200b in breast cancer cells." (PMID 24447584, 2014). "In our study, we identified RAB21, RAB23, RAB18 and RAB3B as novel direct targets of miR-200b in breast cancers." (PMID 24447584, 2014). "Transfection of siRNAs for RAB21, RAB23, RAB18 and RAB3B also inhibits breast cancer cell proliferation and invasion." (PMID 24447584, 2014). "Over-expression of miR-200b or knock-down of RAB21, RAB23, RAB18 and RAB3B inhibited breast cancer cell proliferation and invasion in vitro." (PMID 24447584, 2014). "However, RAB18 appears to be dispensable for LDs maturation and function in several examined cell lines, including HeLa, Cos7, HEK293, and a human mammary carcinoma cell line." (PMID 38607975, 2024). "Members of RAB family, RAB21, RAB23, RAB18 and RAB3B were novel targets regulated by miR-200b in breast cancer, which could be of promising therapeutic significance." (PMID 24447584, 2014).
hepatocellular carcinoma (4 papers, 2014 to 2021). A malignant tumor that arises from hepatocytes. "The expression of RAB18 is also significantly increased in hepatocellular carcinoma and significantly associated with poor prognosis due to increased proliferation and metastasis." (PMID 32432324, 2020). "The CLASH data showed that both miR-30b and miR-30c targeted in coding DNA sequence of Rab18 which was associated with proliferation in hepatocellular carcinoma." (PMID 25249344, 2014). "Our results agreed with the previously study showing that Rab18 was associated with hepatocellular carcinoma (HCC) proliferation." (PMID 25249344, 2014). "miR-455 inhibited cell viability and invasion by directly targeting the 3′-UTR of RAB18 mRNA of hepatocellular carcinoma." (PMID 34135963, 2021). "However, the functions of RAB18 in HCC remain unclear; thus, in the present study, we discovered that miR-455 inhibited cell viability, invasion, and EMT by directly targeting to the 3′-UTR of RAB18 mRNA in hepatocellular carcinoma." (PMID 34135963, 2021).
dengue virus infection (2 papers, 2017 to 2021). "Although FAS recruitment was reported under conditions of dengue virus infection, it required Rab18 to be GTP-associated, consistent with a role for FAS as a Rab18 effector." (PMID 33803444, 2021).